HMGB1 (high mobility group box 1)
Diseases named in the same sentence as HMGB1 in open-access papers (continued):
Sharing a sentence is not in itself a finding about the gene and the disease.
Sepsis (continued). "HMGB1 is a multifunctional nuclear protein and affects a variety of inflammatory reactions by entering the cytoplasm, and scientists have noticed that its interaction with LPS can mediate caspase-11-dependent hepatitis in fatal sepsis." (PMID 36072408, 2022). "In another study, HMGB1 was found to be a biomarker of BBR for sepsis." (PMID 36147356, 2022). "Studies have found that silent information regulator 2-related enzyme 1 and glutamine could ameliorate sepsis-induced AKI by influencing HMGB1 deacetylation or downregulating the HMBG1-mediated pathway." (PMID 36143874, 2022). "Meanwhile, lactylated HMGB1 is secreted and released through the exosome pathway, whereby it damages endothelial integrity and increases vascular permeability, leading to endothelial barrier dysfunction and promoting the development of sepsis." (PMID 36050306, 2022). "This compound was found to protect rats from sepsis by blocking HMGB1 signaling." (PMID 36588685, 2022). "In 1999, it was first reported that HMGB1 could act as a proinflammatory cytokine to stimulate macrophages, which were activated by LPS in sepsis." (PMID 36189354, 2022). "The HMGB1 content in plasma was higher in patients with sepsis than in healthy donors." (PMID 35983056, 2022). "In sepsis survivors, serum HMGB1 levels remain elevated at the time of hospital discharge, and administration of neutralizing anti-HMGB1 antibody beginning at 1 week after the onset of sepsis in animals provided significant protection against cognitive impairment." (PMID 35488237, 2022). "HUVECs were activated with HMGB1 as a late sepsis mediator, followed by treatment with Rg4 for 6 h." (PMID 36142743, 2022). "Many studies from our group and others have revealed that the inhibition of cerebral HMGB1 may attenuate the sepsis-induced brain injury and improve the T-cell-mediated immunity by CPA." (PMID 35832175, 2022). "For example, the administration of HMGB1 antagonists can significantly improve survival of sepsis." (PMID 36465622, 2022). "To determine whether the HMGB1/TLR2/MyD88 signaling pathway is involved in the therapeutic effect of Ts-AES on sepsis-induced ALI, we evaluated protein and mRNA expression levels of HMGB1, TLR2 and MyD88 in lung tissue 12 h after CLP surgery." (PMID 33842398, 2021). "Based on these results, AE improved sepsis via impairing LPS-induced HMGB1 release." (PMID 34493741, 2021). "However, due to the non-tumor specific nature of HMGB1 and the high concentrations thereof, which are also found in the serum and plasma of patients with other acute pathologies such as sepsis and trauma, the use of HMGB1 for tumor diagnosis is questionable." (PMID 33672622, 2021). "Both clinical and non-clinical studies of sepsis have found that the expressions of HMGB1 are in a close association with the nuclear factor kappa-light-chain-enhancer of activated B cells (NF-kB) signalling pathways activation in the cells." (PMID 34575863, 2021). "We suggest that the potent proinflammatory effects of HMGB1 are normally kept in check via sequestration by plasma sialoglycoproteins at physiological pH and zinc levels and are triggered when pH and zinc levels fall in the late stages of sepsis." (PMID 33658363, 2021). "The brain HMGB1 stimulation was capable of inhibiting activation of DCs and inducing differentiation of DCs into anti-inflammatory phenotypes, which further augmented the progression of sepsis-induced immunosuppression." (PMID 34512319, 2021). "This present study showed that HMGB1 disrupted the microvascular endothelial cell barrier, which might be implicated in the pathogenesis of ALI in sepsis." (PMID 34745088, 2021). "Moreover, in a study of sepsis patients with various sources of infection, the kinetics of HMGB1 release showed different patterns according to the primary source of infection." (PMID 33947887, 2021). "It is reported that HMGB1 could mediate the treatment of sesamin on sepsis by modulating the pro-inflammatory cytokines." (PMID 34784841, 2021).
Sepsis (continued). "High mobility group box 1 (HMGB1) has been identified as a critical mediator of severe sepsis." (PMID 34567165, 2021). "Elevated HMGB1 mediates cognitive decline in sepsis survivors in mice." (PMID 33925132, 2021). "In humans, HMGB1 circulatory levels persistently increase in severe sepsis and septic shock." (PMID 34743181, 2021). "The fact that HMGB1 acts late in sepsis opens a therapeutic window for medical treatment." (PMID 33925132, 2021). "The pretreatment of a mouse macrophage-like cell line, Raw 264.7, with sulfated galactocerebroside (sulfatide, SM4) was found to hinder LPS-induced TLR4 colocalization with CTxB-positive ganglioside-rich microdomains, suppressing the secretion of a sepsis mediator, high mobility group box 1 (HMGB1)." (PMID 34502474, 2021). "Similarly, targeting HMGB1 with a specific antibody promoted neutrophil activity, attenuated post-sepsis immunosuppression and conferred resistance to secondary bacterial infection." (PMID 33925132, 2021). "HMGB1, a nuclear binding protein, once exteriorized, serves as a mediator of inflammation and coagulation, and hence represents as a novel treatment target in sepsis and thrombosis." (PMID 34235204, 2021). "In another study, also focused on the roles of PKM2 and HMGB1 in sepsis, the authors demonstrated that macrophage inflammasome activation and aerobic glycolysis might promote the pathological progression of the disease." (PMID 33503959, 2021). "Platelet-derived high mobility group box-1 (HMGB1) may also play a critical role in sepsis-mediated thrombosis resulting in complications like disseminated intravascular coagulation and multiple organ failure." (PMID 34235204, 2021). "Down regulation of miR-205-5b increased HMGB1 expression in LPS-induced sepsis." (PMID 34956235, 2021). "SIRT1-regulated deacetylation of HMGB1 inhibits sepsis-induced AKI." (PMID 34250012, 2021). "A recent study has unraveled the critical role of circulating HMGB1 in mediating lethal sepsis." (PMID 34824200, 2021). "Interaction of HMGB1 with Toll-like receptors (TLRs) during sepsis is well-documented." (PMID 33658363, 2021). "Although the details of the dysregulated host response during sepsis have not yet been clarified, previous studies have suggested that high mobility group box 1 protein (HMGB1) may play a significant role in sepsis-induced lethality." (PMID 34107884, 2021). "Currently, the influence of aberrant HMGB1 expression in sepsis has been explored." (PMID 34784841, 2021). "HMGB1, acting as an inflammatory mediator, is responsible for the production and release of proinflammatory cytokines in many inflammatory and infectious disorders, including acute lung injury, liver ischemia-reperfusion injury, and sepsis." (PMID 35005033, 2021). "Since annexin A5 inhibits HMGB-1 interaction with TLR4 in models of sepsis and inflammation, it could interfere with HMGB1-mediated SARS-CoV-2 infection." (PMID 34566657, 2021). "A programmed nuclear-cytoplasmic translocation of HMGB1 is a prerequisite in innate immune cells for active HMGB1 release via exocytosis of cytoplasmic vesicles such as secretory lysosomes or via exosomal release during sepsis." (PMID 34685772, 2021). "Our investigation examined and discovered that HMGB1 might be a downstream signaling component of miR-381-3p in sepsis by the luciferase results." (PMID 34784841, 2021). "A recent article has shown that in lethal sepsis, HMGB1 can mediate caspase-11-induced pyroptosis." (PMID 34743181, 2021). "It has also been suggested that HMGB1 could be used as a late marker of sepsis, although our results showed increased levels of HMGB1 not only in septic shock but in sepsis patients." (PMID 34576097, 2021). "Sepsis-induced inflammation wasassessed by measuring interleukin-6 (IL-6), IL-10 and HMGB1 levels." (PMID 33605309, 2021). "Moreover, a positive correlation was verified between the sepsis serum EVs-HMGB1 level and clinical liver damage." (PMID 34743181, 2021).
Sepsis (continued). "Treatment with monoclonal anti-HMGB1 antibodies would ameliorate tissue injury in the sepsis model." (PMID 34567165, 2021). "Patients with sepsis undergo an inflammatory response driven by continuous or late HMGB1 release." (PMID 34250012, 2021). "The release of HMGB1 leads to injury of multiple organs during sepsis." (PMID 34410682, 2021). "The results of our study suggest that plasma HMGB1 may be a potential biomarker for severity assessment and mortality prediction of sepsis." (PMID 33947887, 2021). "In fact, patients who survive severe sepsis maintain a continuously high HMGB1 circulatory level." (PMID 34743181, 2021). "Despite the discovery of the important role of HMGB1 in microglia activation, the mechanism of HMGB1 in sepsis neuroinflammation remains unclear." (PMID 33952191, 2021). "The extracellular vesicle HMGB1 was detected in the serums of sepsis patients." (PMID 34743181, 2021). "Therefore, we concluded that circTLK1 contributed to sepsis-associated AKI by regulating inflammation and oxidative stress through the miR-106a-5p/HMGB1 axis." (PMID 34250012, 2021). "Circulating HMGB1 acts on macrophages as an inflammatory cytokine in later stages of sepsis." (PMID 33925132, 2021). "Interestingly, the recently identified triggering receptor expressed on myeloid cell-1 engages in HMGB1-dependent NF-κB activation, resulting in the release of pro-inflammatory mediators during sepsis progression." (PMID 33925132, 2021). "Thus, in situations where there are high plasma LPS levels, like during sepsis, brain cells become more responsive to HMGB1." (PMID 34208101, 2021). "Here, our study explored the potential ceRNA network in septic mouse models and identified that lncRNA GAS5 could interact with miR-449b and HMGB1, and further promote the sepsis-induced myocardial depression with the activation of the NF-κB signaling pathway." (PMID 33645622, 2021). "Moreover, increased circulating levels of HMGB1 have been described in experimental sepsis models, as well as in patients with bacterial sepsis." (PMID 34360659, 2021). "Thus, a drop in pH and zinc concentration in sepsis can release sequestered HMGB1 and trigger the inflammatory cascade." (PMID 33658363, 2021). "According to reports, HMGB1 plays an important role in neurotoxicity in glial cell activation, but its role in sepsis neuroinflammation remains unclear." (PMID 33952191, 2021). "CircTLK1 sponged miR‐17‐5p to aggravate mtDNA oxidative damage, mitochondrial dysfunction and cardiomyocyte apoptosis via activating PARP1/HMGB1 axis during sepsis, indicating that circTLK1 may be a putative therapeutic target for septic cardiomyopathy." (PMID 34410682, 2021). "Besides, it also restores the balance of CD4+/CD8+ and Th1/Th2 ratio and reduces the concentrations of IL-6, TNF-α, and HMGB1, thus inhibiting the systemic inflammatory response induced by sepsis to alleviate lung injury." (PMID 34057015, 2021). "The role of high-mobility group box-1 (HMGB1) in outcome prediction in sepsis is controversial." (PMID 33947887, 2021). "Neutralizing antibodies against HMGB1 reverse the lethality of established sepsis in mice, indicating that HMGB1 may be a therapeutic target for sepsis with a clinically relevant therapeutic window." (PMID 34107884, 2021). "Overexpression of miR-381-3p could repress the mRNA expression of HMGB1, inhibit the cell apoptosis and inflammatory response, and motivate the viability of sepsis cells." (PMID 34784841, 2021). "Further characterizing HMGB1 as a sialic acid-binding lectin, we found that optimal binding takes place at normal blood pH and is markedly reduced when pH is adjusted with lactic acid to levels found in sepsis." (PMID 33658363, 2021). "HMGB1 plays a role in inflammatory regulation and stress response; it is an important inflammatory mediator in the late phase of sepsis and a late predictor of mortality in sepsis patients." (PMID 34745104, 2021).
Sepsis (continued). "Taken together, current study sheds light on the development of HMGB1-targeting therapeutics and might open a new avenue to treat many immune disorders, such as sepsis." (PMID 33854044, 2021). "Together, these findings support the notion that HMGB1 is a drug-target in lethal immune disorders and might bring potential therapeutics for the treatment of sepsis." (PMID 33854044, 2021). "TLR4 plays a role in LPS and HMGB1-induced apoptosis in PBMCs of patients with sepsis." (PMID 34733114, 2021). "Inhibition of cerebral HMGB1 downregulated ChAT expression but resulted in increased expression of AchE, indicating that HMGB1 might be responsible for hyperactivation of the brain cholinergic system under sepsis." (PMID 34512319, 2021). "Thus, HMGB1-mediated hyperactivation of innate immunity in sepsis requires acidosis, and micromolar zinc concentrations are protective." (PMID 33658363, 2021). "Furthermore, the study and its outcomes suggest that necroptosis is likely a major source of plasma HMGB1 in sepsis." (PMID 33947887, 2021). "As an in vivo ligand for RAGE, HMGB1 is essential to the inflammatory response of sepsis." (PMID 33436632, 2021). "HMGB1 is known to be a late-appearing inflammatory cytokine during sepsis." (PMID 33732235, 2021). "Thus, the beneficial effect of RAGE inhibition in sepsis is at least partially attributed to inhibition of one of its ligands, HMGB1." (PMID 33436632, 2021). "We attempted to demonstrate whether AE can impair LPS-induced lactate and HMGB1 release during sepsis." (PMID 34493741, 2021). "Meanwhile, we found miR-449b could bind to the downstream HMGB1 via bioinformatics prediction and luciferase assays (all P<0.01), and the mRNA and protein levels of HMGB1 were elevated in mice with sepsis." (PMID 33645622, 2021). "In vivo models of sepsis have demonstrated that HMGB1 could be found 8 h after the onset of sepsis with a peak occurring between 16 and 32 h." (PMID 33732235, 2021). "Furthermore, DS has also been reported to dose-dependently attenuate endotoxin-induced HMGB1 release in macrophage and monocyte cultures, while HMGB1 has been a late mediator of lethal sepsis." (PMID 34938184, 2021). "This cell-based system allows us to screen thousands of different small molecules in a short time and to find the candidates that might effectively inhibit the activation of HMGB1-caspase-11-GSDMD pathway in sepsis." (PMID 33854044, 2021). "A prior study has demonstrated that recombinant HMGB1 mediated cytosolic translocation of LPS and induced caspase-11–dependent immune responses in sepsis and has uncovered that HMGB1 could be a potential pharmacological target for treating sepsis." (PMID 34093202, 2021). "Targeting HMGB1 directly or toward HMGB1-receptor signaling could be a promising approach in treating sepsis, arthritis, cancer, diabetes, and JIA." (PMID 34247641, 2021). "Given the critical impact of DAMPs in sepsis, our data of eCIRP-mediated reduction of B-1a cell numbers in the peritoneal cavity directs a new pathophysiological avenue for identifying the possible impacts of other DAMPs like HMGB1, H3, and ATP on B-1a cells in sepsis." (PMID 34058975, 2021). "Similarly, using transgenic mouse models, others have shown that deletion of AMPKα in myeloid cells exacerbates polymicrobial sepsis by promoting the release of HMGB1 and endotoxic shock, while activation of AMPK had protective effects." (PMID 33616039, 2021). "Thus, targeting the HMGB1 conformation that attenuates the binding with LPS would be a potential approach in the treatment of sepsis." (PMID 34093202, 2021). "The average levels of HMGB1 were approximately 5- and 26-fold higher than the normal range in the peripheral blood of patients with nonsevere and severe COVID-19, respectively, reaching levels typically observed with severe sepsis." (PMID 34616852, 2021).
Sepsis (continued). "It suggested that TN domain-specific mAbs may confer protection against lethal sepsis partly by preventing harmful TN/HMGB1 interaction that may adversely trigger macrophage pyroptosis and immunosuppression." (PMID 34571869, 2021). "HMGB-1 is considered a mediator of systemic inflammation in the relative late phase of sepsis." (PMID 33859538, 2021). "HMGB1 has previously been shown to circulate in the bloodstream during endotoxemia and sepsis." (PMID 33546173, 2021). "Thus, using HMGB1 plus LPS for screening the effective and specific inhibitor of caspase-11 signaling would be promising in the development of medicine for treating sepsis." (PMID 34093202, 2021). "Current studies have demonstrated that HMGB1, the late mediating factor in sepsis pathogenesis and an essential factor that mediates cognitive impairment in sepsis survivors, triggers and sustains the inflammatory response by inducing cytokine release and recruiting leucocytes." (PMID 34867376, 2021). "HMGB1 plays important roles in inflammation diseases such as sepsis and acute liver injury." (PMID 34113251, 2021). "Our study suggested that GAS5 might promote sepsis-induced myocardial depression via the miR-449b/HMGB1 axis and the following NF-κB activation." (PMID 33645622, 2021). "Interestingly, when we measured the protein HMGB1 in human plasma, we found the maximum increase in the group of sepsis patients." (PMID 34576097, 2021). "Since HMGB1 deletion is lethal, circPTK2 could be the target in therapeutics for sepsis-induced cognitive dysfunction." (PMID 33952191, 2021). "Inflammatory biomarkers, such as interleukin-6 (IL-6), neutrophil gelatinase-associated lipocalin (NGAL), and high-mobility group box 1 (HMGB1), have been effective at differentiating sepsis, predicting prognosis, and monitoring treatment in patients in the ICU." (PMID 32635454, 2020). "However, it would be important to promote a greater understanding of the role of HMGB1 in the pathological process of the development of sepsis organ injury." (PMID 32943679, 2020). "At present, there are relatively few studies on the immunosuppressive effect of HMGB1 in sepsis." (PMID 33552058, 2020). "Therefore, in order to provide more accurate targeted therapy for sepsis, more detailed studies on HMGB1 are needed." (PMID 33552058, 2020). "Our results thus indicate that HMGB1 may be one of the potential target molecules for the therapeutic strategy using STAT3 decoy ODNs in sepsis treatment." (PMID 32943679, 2020). "Perhaps the final balance of these effects determines whether the role of HMGB1 in sepsis is beneficial or harmful." (PMID 33552058, 2020). "The authors concluded that these observations revealed the previously unrecognized involvement of platelet-derived HMGB1 in the regulation of neutrophil recruitment and activation by modulating platelet activation during sepsis, presumably augmented via the participation of PF4." (PMID 33042161, 2020). "However, a consensus on how HMGB1 applies its immunomodulatory function in sepsis remains to be further demonstrated." (PMID 33552058, 2020). "Furthermore, andrographolide administered via intravenous injection was able to reduce sepsis-induced HMGB-1 production, inhibit vascular leakage, and improve the survival rate of CLP-treated mice." (PMID 33193799, 2020). "Therefore, HMGB1 participates in the release of pro-inflammatory factors in sepsis in a variety of ways." (PMID 33552058, 2020). "Sepsis or ARDS triggers HMGB1, thus strongly activating the innate immunity." (PMID 32724296, 2020). "HMGB1 plays a unique role in the development of post-sepsis immunosuppression." (PMID 33552058, 2020). "Therefore, HMGB1 is a decisive inflammatory mediator and can be considered as a new target in the treatment of sepsis." (PMID 32197507, 2020). "Furthermore, contributions of extracellular HMGB1 in pathogenesis have been reported for various diseases including sepsis, arthritis, ischaemia–reperfusion injury, and neurodegeneration." (PMID 33318474, 2020).